PRDM15 (PR/SET domain 15)
Description:
Sequence-specific DNA-binding transcriptional regulator. Plays a role as a molecular node in a transcriptional network regulating embryonic development and cell fate decision. Stimulates the expression of upstream key transcriptional activators and repressors of the Wnt/beta-catenin and MAPK/ERK pathways, respectively, that are essential for naive pluripotency and self-renewal maintenance of embryonic stem cells (ESCs). Specifically promotes SPRY1 and RSPO1 transcription activation through recognition and direct binding of a specific DNA sequence in their promoter regions. Involved in early embryo development (By similarity). Also plays a role in induced pluripotent stem cells (iPSCs) reprogramming.
Synonyms: C21orf83; ZNF298; PFM15
Tractability: PROTAC: UniProt records ubiquitination sites on it; ubiquitination databases record sites on it.
Gene: Protein-coding gene on chromosome 21 (41,798,225 to 41,879,482, reverse strand). Ensembl gene ENSG00000141956.
Subcellular location: Nucleus
Subcellular location (Human Protein Atlas): Nuclear bodies; Nucleoplasm
Gene Ontology:
Molecular function: DNA-binding transcription activator activity, RNA polymerase II-specific; promoter-specific chromatin binding; RNA polymerase II cis-regulatory region sequence-specific DNA binding
Biological process: negative regulation of MAPK cascade; positive regulation of canonical Wnt signaling pathway; positive regulation of transcription by RNA polymerase II; regulation of stem cell division; regulation of transcription by RNA polymerase II
Cellular component: nuclear body; nucleoplasm; nucleus
Genetic constraint (gnomAD): Loss-of-function variants: 61 observed, 124.25 expected, observed/expected ratio (o/e) 0.49, 90% interval 0.4 to 0.61. The upper end of that interval is the gene's LOEUF score, 0.61, which puts it in group 2 of 6, group 1 being the genes least tolerant of losing a copy. Missense variants: 1,213 observed, 1,552.9 expected, observed/expected ratio (o/e) 0.78, 90% interval 0.74 to 0.82. Synonymous variants: 604 observed, 611.97 expected, observed/expected ratio (o/e) 0.99, 90% interval 0.92 to 1.06.
Homologues: Orthologues: chimpanzee PRDM15 (99% identical), macaque PRDM15 (99% identical), dog PRDM15 (94% identical), mouse Prdm15 (91% identical), rat Prdm15 (91% identical), pig PRDM15 (88% identical), guinea pig PRDM15 (84% identical), tropical clawed frog prdm15 (72% identical), zebrafish PRDM15 (60% identical). Paralogues in human: ZFAT (17% identical), ZBTB11 (14% identical), ZFY (13% identical), ZFX (13% identical), ZNF304 (13% identical), ZNF551 (12% identical), E4F1 (12% identical), ZNF256 (12% identical), ZNF711 (12% identical), ZNF792 (12% identical), ZNF549 (11% identical), ZNF418 (11% identical), and 26 more.